KRTAP5-4 (keratin associated protein 5-4)
Description:
In the hair cortex, hair keratin intermediate filaments are embedded in an interfilamentous matrix, consisting of hair keratin-associated protein (KRTAP), which are essential for the formation of a rigid and resistant hair shaft through their extensive disulfide bond cross-linking with abundant cysteine residues of hair keratins. The matrix proteins include the high-sulfur and high-glycine-tyrosine keratins.
Synonyms: KRTAP5.4
Gene: Protein-coding gene on chromosome 11 (1,620,958 to 1,622,138, reverse strand). Ensembl gene ENSG00000241598.
Genetic constraint (gnomAD): Missense variants: 129 observed, 162.27 expected, observed/expected ratio (o/e) 0.79, 90% interval 0.69 to 0.92. Synonymous variants: 55 observed, 62.82 expected, observed/expected ratio (o/e) 0.88, 90% interval 0.7 to 1.1.
Homologues: Paralogues in human: KRTAP5-3 (76% identical).
Diseases named in the same sentence as KRTAP5-4 in open-access papers:
KRTAP5-4 is named in the same sentence as 4 diseases in open-access papers, as found by Europe PMC text mining. Sharing a sentence is not in itself a finding about the gene and the disease.
KRTAP5-4 shares sentences with these, for which no sentence is quoted: breast carcinoma (2 papers); adenoma (1); metastatic tumors (1); stomach adenocarcinoma (1).